FDX1 (ferredoxin 1)
Diseases named in the same sentence as FDX1 in open-access papers (continued):
Sharing a sentence is not in itself a finding about the gene and the disease.
gastric cancer (20 papers, 2022 to 2026). A primary or metastatic malignant neoplasm involving the stomach. "Our study reveals that FDX1 is intimately linked to energy and substrate metabolism in gastric cancer, predominantly observed in patients with the CSRS‐Low subtype and associated with a more favorable prognosis." (PMID 38898987, 2024). "Specifically, lactylation of methyltransferase-like protein 16 (METTL16) at lysine 229 induces m6A modification of ferredoxin 1 (FDX1) mRNA, leading to elevated FDX1 expression and enhanced cuproptosis in gastric cancer cells." (PMID 41152975, 2025). "Future studies should focus on validating the functional role of cuproptosis-related genes, particularly FDX1, in gastric cancer cells and animal models." (PMID 40410601, 2025). "The prognostic model combining FDX1, PDHA1, and LIAS expression has the potential to classify gastric cancer patients into different risk categories as biomarkers for personalized treatment strategies." (PMID 41158129, 2025). "METTL16 K229 upregulates ferredoxin 1 in gastric cancer, disrupting copper metabolism and inducing cuproptosis." (PMID 40994548, 2025). "FDX1 gene expression was found to be upregulated in gastric cancer patients, suggesting a pro-carcinogenic role of these proteins." (PMID 39068453, 2024). "Emerging research proved METTL16-mediated m6A modification on FDX1 mRNA was critical for cuproptosis in gastric cancer (GC), and METTL16 lactylation significantly promoted the therapeutic efficacy of the copper ionophore-elesclomol." (PMID 39329964, 2024). "Lactate-induced lactylation of METTL16 at lysine 229 promotes m6A modification of FDX1 mRNA, resulting in increased FDX1 mRNA expression and subsequent copper-dependent cell death in gastric cancer." (PMID 39325940, 2024). "Here the authors find that copper promotes METTL16 lactylation, inducing cuproptosis via stabilizing FDX1 in gastric cancer." (PMID 37863889, 2023). "Notably, upregulation of FDX1 significantly suppressed lymph node metastasis of gastric cancer cells in a mouse popliteal lymph node metastasis model." (PMID 42107026, 2026). "METTL16 was reported to promote cuproptosis in gastric cancer through the m6A modification of FDX1." (PMID 40069867, 2025). "However, in another study, gastric cancer patients with high expression of the FDX1, LIAS, SLC31A1, DLAT, and ATP7A/B genes demonstrated a better prognosis." (PMID 39068453, 2024). "In gastric cancer, by increasing the FDX1 mRNA m6A modification, METTL16 could evaluate the cuproptosis sensitivity of cancer cells." (PMID 38797784, 2024). "For instance, in gastric cancer, it promotes lactylation at the K229 site of METTL16, which in turn mediates the m6A modification on FDX1 mRNA, thereby enhancing cuproptosis." (PMID 40276654, 2025). "High copper content in gastric cancer tissues promotes lactylation of methyltransferase-like protein 16 (METTL16) and ultimately induces cuproptosis in GC cells by upregulating FDX1 protein levels." (PMID 40897695, 2025). "In gastric cancer, the lactylation of METTL16 promotes cuproptosis through m6A modification on FDX1 mRNA." (PMID 40276654, 2025). "In gastric cancer, METTL16 K229la increases m6A modification of ferredoxin 1 mRNA, which triggers cuproptosis." (PMID 40994548, 2025). "The combination of the SIRT2 inhibitor AGK2 and elesclomol promotes cuproptosis in gastric cancer cells by enhancing the lactylation of METTL16 at lysine 229 and increasing FDX1 protein levels." (PMID 40897695, 2025). "We conducted molecular experiments to validate our findings, and the results of Western blot analysis revealed notable disparities in the expression levels of FDX1, LIAS, DLAT, DLST, GCSH, PDHB and PDHA1 in gastric cancer cells between the CSRS‐Low (AGS) and CSRS‐High (HGC‐27) subtypes." (PMID 38898987, 2024).
gastric cancer (continued). "Some of these markers have been identified for their potential functions in cancer: FDX1 can be activated by SF1 and cJUN in Leydig cells, CDKN2a usually functions as a tumor suppressor in many cancers, and DLAT has also been reported to be an oncogene in gastric cancer." (PMID 37190215, 2023). "FDX1 is especially expressed in SKCM, immune, and non-immune cells of stomach cancer cells, as shown by the scRNA-seq data from the HPA database." (PMID 37298135, 2023).
lung carcinoma (20 papers, 2021 to 2025). "There has been a research on single-nucleotide polymorphisms (SNPs) in cuproptosis-related genes demonstrating that FDX1-rs10488764 was associated with an increased risk of lung cancer." (PMID 36226187, 2022). "However, limited information is available regarding the association between FDX1 and lung cancer." (PMID 38883186, 2024). "Understanding the interplay between Ferredoxin 1 and metabolic pathways in KRAS mutant lung cancer provides valuable insights into the underlying mechanisms driving tumorigenesis and identifies potential targets for therapeutic intervention." (PMID 38802900, 2024). "According to several studies, FDX1 affects lung cancer prognosis by regulating fatty acid oxidation." (PMID 37193786, 2023). "In a recent lung cancer study, knockdown of FDX1 improved mitochondrial metabolic dysfunction, thereby reducing the inflammatory response of the body." (PMID 37809099, 2023). "Recently, a study showed that FDX1 was decreased, and the patients with lower expression of FDX1 had a worse prognosis for lung cancer." (PMID 36536785, 2022). "In a word, our study showed that FDX1, a key enzyme for cuproptosis, affected the prognosis of lung cancer patients by influencing the expression of GLS, PDHA1, PDHB, DLAT, and MTF1." (PMID 36620594, 2022). "In closing, our data showed that FDX1 affected the prognosis of lung cancer by altering the expression of cuproptosis-related signature." (PMID 36620594, 2022). "Lung cancer risk was shown to be elevated by the minor alleles of SLC31A1-rs10981694 and FDX1-rs10488764." (PMID 36454396, 2022). "As far as we know, our study was the first investigation illustrating the correlation between FDX1 protein expression and unfavorable prognosis of lung cancer patients by tissue microarray." (PMID 36620594, 2022). "A high phosphorylation level was correlated with the FDX1 site of S177 in lung cancer." (PMID 37298135, 2023). "In addition, FDX1 has the ability to increase ATP production and affect glucose metabolism, amino acid metabolism, and cell proliferation in lung cancer cells." (PMID 37763758, 2023). "FDX1 was reported to be related to the prognosis of patients with lung cancer." (PMID 37007145, 2023). "FDX1 expression was identified by immunohistochemical staining in 301 lung cancer samples." (PMID 36620594, 2022). "FDX1 affects the prognosis of lung cancer by altering the expression of cuproptosis-related signature (GLS, PDHA1, PDHB, MTF1, and DLAT), which more strongly confirms that the prognosis of lung cancer patients is closely related to the occurrence of cuproptosis." (PMID 36620594, 2022). "FDX1 as the bridge between unfavorable prognosis of lung cancer patients and cuproptosis." (PMID 36620594, 2022). "Overall, in our results, we found that FDX1 knockdown may decrease glutamine, and we speculated that FDX1 was likely to be a potential target in lung cancer treatment." (PMID 34690780, 2021). "In summary, o8G-modified circKIAA1797 inhibits cellular cuproptosis through FDX1, LIPT1 and the mPTP and promotes lung cancer development." (PMID 40176113, 2025). "CircKIAA1797 inhibits cuproptosis by inhibiting ferredoxin 1 (FDX1) expression and promotes lung cancer development." (PMID 40710359, 2025). "Stratification by pathological type revealed that the high expression group of FDX1 had a better prognosis than the low expression group in both LUAD and other lung cancer patients." (PMID 36620594, 2022). "Ferredoxin 1, as a central mediator in cellular redox regulation and metabolism, likely plays a pivotal role in orchestrating these metabolic adaptations in KRAS mutant lung cancer." (PMID 38802900, 2024). "Similarly, the study also found that ferredoxin 1 (FDX1) has a positive effect on cuproptosis, and buthionine sulfoximine (BSO) has a certain role in the cuproptosis mechanism of lung cancer cells." (PMID 36338998, 2022).
lung carcinoma (continued). "The conclusion of the cuproptosis-independent role of FDX1 is consistent with previous results from other researchers, which showed that knockdown of FDX1 failed to alter cell growth and cell apoptosis in lung cancer cells but reduced ATP production." (PMID 36611966, 2022). "FDX1 was significantly downregulated in LUAD, which may be related to the escape of cuproptosis in lung cancer cells." (PMID 36712848, 2022).
thyroid cancer (16 papers, 2022 to 2026). "It was shown that FDX1 expression was lower in samples with thyroid cancer-containing material compared to healthy tissue." (PMID 39940256, 2025). "ES inhibited the growth of thyroid cancer cells by increasing cuproptosis while simultaneously increasing Cu levels and FDX1 expression compared to control groups." (PMID 39940256, 2025). "On the contrary, FDX1 displayed weak-to-moderate cytoplasmic positivity in thyroid cancer, colorectal cancer, liver cancer, and melanoma." (PMID 36210836, 2022). "Based on the proteomic assessment of FDX1 expression profiles in cancer cell lines, neuroblastoma, thyroid cancer, and kidney cancer were ranked as the top three cancers with the lowest expression." (PMID 36186457, 2022). "Our results showed that FDX1 was dysregulated in 17 types of cancer, and IHC analysis confirmed this tendency at the protein level in thyroid cancer, colorectal cancer, and liver cancer." (PMID 36210836, 2022). "In thyroid cancer, FDX1 knockdown has been shown to suppress cell death induced by cuproptosis." (PMID 40244269, 2025). "Emerging research has shown that knockdown of FDX1 decreases the lipoylation levels of DLAT and DLST in thyroid cancer cells, inhibiting copper-induced cancer cell death." (PMID 40897695, 2025). "New research has found that knockdown of FDX1 reduces the level of lipoylation of DLAT and DLST in thyroid cancer cells, and copper-induced cancer cell death is inhibited." (PMID 40897695, 2025). "The three-gene model (FDX1, BUB1, RPL3) was constructed to predict DFS of 1, 3 and 5 years in thyroid cancer (AUC: 0.789, 0.733, 0.757)." (PMID 37745716, 2023). "Three CRG models (FDX1, BUB1, RPL3) could better predict the prognosis of thyroid cancer." (PMID 37745716, 2023).
breast carcinoma (14 papers, 2022 to 2025). "Notably, elevated levels of FDX1 expression have been linked to improved overall survival and progression-free survival in breast cancer patients." (PMID 39702350, 2024). "Although FDX1 plays a crucial role in mediating cuproptosis, its biological function in breast cancer remains largely unelucidated." (PMID 39976173, 2025). "We then constructed a cuproptosis-related signature with six genes (DKN2A, MTF1, PDHA1, DLD, LIPT1, and FDX1) for breast cancer, which predicted the OS rate with an accuracy that ranged from medium to high." (PMID 36312586, 2022). "In qPCR expression of 10 pairs of breast cancer and adjacent samples, FDX1, key upstream gene of cuproptosis pathway, downregulated in cancer samples." (PMID 36699089, 2022). "Multiomics approaches were used to create a cuproptosis-related signature with six genes (DKN2A, MTF1, PDHA1, DLD, LIPT1, and FDX1) for breast cancer." (PMID 36312586, 2022). "In conclusion, multiomics approaches were conducted to develop a cuproptosis-related signature with six genes (DKN2A, MTF1, PDHA1, DLD, LIPT1, and FDX1) for breast cancer." (PMID 36312586, 2022). "Studies have shown that FDX1 expression is down-regulated in breast cancer." (PMID 39702350, 2024). "As the critical gene of cuproptosis, high expression of FDX1 was related to favorable prognoses in breast cancer patients; thus, it might be a potential prognostic marker." (PMID 39432636, 2024). "In the cohort study, high expression of LIAS, FDX1, LIPT1, DLD, PDH1, and ATP7B, coupled with low CDKN2A expression, was associated with favorable RFS in patients with estrogen receptor-positive early breast cancer (ER+ EBC)." (PMID 39867656, 2024). "Another vital discovery of our research was that we developed a cuproptosis-related prognostic signature containing six genes (CDKN2A, MTF1, PDHA1, DLD, LIPT1, and FDX1) for breast cancer, which predicted the OS rate with an accuracy that ranged from medium to high." (PMID 36312586, 2022). "The critical gene FDX1 might be a prognostic marker in breast cancer." (PMID 39432636, 2024). "After internalization by mouse 4T1 breast cancer cells, Cu+ coupled with ES induced DLAT oligomerization and the downregulation of Fe‒S cluster proteins, such as ferredoxin 1 (FDX1) and dihydrolipoamide dehydrogenase (DLD), ultimately leading to cuproptosis." (PMID 39554839, 2024). "Prognosis analysis revealed poor OS and RFS rates in breast cancer patients with elevated levels of CDKN2A and PDHA1 and low levels of MTF1, DLD, LIPT1, and FDX1." (PMID 36312586, 2022). "qPCR results showed that two model lncRNAs (USP2-AS1, NIFK-AS1) and three Cuproptosis genes (FDX1, PDHA1, DLAT) expressed differently between 10 pairs of breast cancer tissue samples and adjacent samples." (PMID 36699089, 2022). "FDX1, PDHA1 and DLAT also significantly down regulated in breast cancer." (PMID 36699089, 2022). "FDX1 (P < 1E‐12), LIAS (P = 2.22E‐16), LIPT1 (P < 1E‐12), DLD (P < 5.46E‐09), DLAT (P = 3.14E‐02), PDHA1 (P = 1.15E‐07), MTF1 (P = 1.07E‐09), and GLS (P = 2.48E‐05) were downregulated in breast cancer, while PDHB (P = 5.04E‐07) and CDKN2A (P = 1.62E‐12) were upregulated." (PMID 39432636, 2024). "Therefore, FDX1, LIPT1, and PDHB have favorable prognostic values before breast cancer recurrence." (PMID 39432636, 2024). "As cuproptosis-promoting genes, FDX1, LIAS, LIPT1, DLD, DLAT, and PDHA1 were under-expressed in breast cancer; at the same time, CDKN2A, which inhibited cuproptosis, was over-expressed in breast cancer, suggesting that cuproptosis might involve in the protective mechanism of BRCA." (PMID 39432636, 2024). "In breast cancer cell, lack of FDX1 may lead to the failure in startup of this “suicide” mechanism, leading to the escape of breast cancer cells from cuproptosis." (PMID 36699089, 2022).
colon adenocarcinoma (14 papers, 2022 to 2025). "FDX1 expression in colon adenocarcinoma (COAD) is positively associated with “quiescence” and “inflammation” but negatively correlated with “invasion”, and the expression of FDX1 is positively correlated with infiltration levels of CD8+ T cells, NK cells, and neutrophils." (PMID 36466876, 2022). "At first, from TCGA database, it was confirmed that the FDX1 expression was down-regulated in COAD (colon adenocarcinoma) tissues (p = 0.0015)." (PMID 38520567, 2025). "In this work, at first, through TCGA database, it was revealed that FDX1 exhibited lower expression in COAD (colon adenocarcinoma) tissues, and CRC patients with lower FDX1 expression had worse prognosis." (PMID 38520567, 2025). "Flow cytometer was executed to detect CD4+ and CD8+ T cell immunoinfiltration levels in colon adenocarcinoma (COAD) patients with high FDX1 expression, results of which were completely consistent with TIMER database analysis." (PMID 37984863, 2024). "The effect of FDX1 expression on various diseases, such as clear cell carcinoma, colon adenocarcinoma, and polycystic ovary syndrome, has aroused broad concern." (PMID 38628140, 2024). "In colon adenocarcinoma (COAD), FDX1 expression has a strong correlation with tumor immunity, especially CD8+ T cells and CD4+ T cells, and the pathogenesis of COAD." (PMID 39329964, 2024). "However, the role of FDX1 in the pathogenesis of colon adenocarcinoma (COAD) remains to be studied." (PMID 36173462, 2023). "Interestingly, one report has uncovered that the expression of FDX1 in colon adenocarcinoma (COAD) tissues is significantly lower than that in normal tissues, and the overall survival rate of COAD patients with FDX1 high expression group is better than that in patients with FDX1 low expression." (PMID 38520567, 2025).